FIS1 (fission, mitochondrial 1)
Description:
Involved in the fragmentation of the mitochondrial network and its perinuclear clustering. Plays a minor role in the recruitment and association of the fission mediator dynamin-related protein 1 (DNM1L) to the mitochondrial surface and mitochondrial fission. May not be essential for the assembly of functional fission complexes and the subsequent membrane scission event. Also mediates peroxisomal fission. May act when the products of fission are directed toward mitochondrial homeostasis, mitophagy, or apoptosis. Can induce cytochrome c release from the mitochondrion to the cytosol, ultimately leading to apoptosis.
Synonyms: TTC11; CGI-135; H_NH0132A01.6
Tractability: Antibody: UniProt predicts a signal peptide or a membrane-spanning region. PROTAC: UniProt records ubiquitination sites on it; ubiquitination databases record sites on it; its protein half-life has been measured.
Gene: Protein-coding gene on chromosome 7 (101,239,458 to 101,252,316, reverse strand). Ensembl gene ENSG00000214253.
Subcellular location: Mitochondrion outer membrane; Peroxisome membrane
Subcellular location (Human Protein Atlas): Mitochondria
Pathways (Reactome):
Protein localization: Class I peroxisomal membrane protein import
Gene Ontology:
Molecular function: identical protein binding; lipid binding; molecular adaptor activity; protein binding
Biological process: mitochondrial fission; mitochondrion organization; negative regulation of ATP metabolic process; negative regulation of fatty acid transport; peroxisome fission; positive regulation of intrinsic apoptotic signaling pathway; cellular response to glucose stimulus; cellular response to lipid; cellular response to peptide; cellular response to toxic substance; mitochondrial fragmentation involved in apoptotic process; positive regulation of mitochondrial fission; positive regulation of neuron apoptotic process; response to endoplasmic reticulum stress; response to flavonoid; response to fluoride; response to hypobaric hypoxia; response to muscle activity; response to nutrient levels
Cellular component: membrane; mitochondrial outer membrane; mitochondrion; peroxisomal membrane; peroxisome; protein-containing complex; cytosol
Genetic constraint (gnomAD): Loss-of-function variants: 16 observed, 22.1 expected, observed/expected ratio (o/e) 0.72, 90% interval 0.49 to 1.1. The upper end of that interval is the gene's LOEUF score, 1.1, which puts it in group 4 of 6, group 1 being the genes least tolerant of losing a copy. Missense variants: 198 observed, 198.02 expected, observed/expected ratio (o/e) 1, 90% interval 0.89 to 1.12. Synonymous variants: 92 observed, 85.4 expected, observed/expected ratio (o/e) 1.08, 90% interval 0.91 to 1.28.
Homologues: Orthologues: chimpanzee FIS1 (100% identical), pig FIS1 (97% identical), guinea pig FIS1 (97% identical), mouse Fis1 (96% identical), dog FIS1 (93% identical), macaque FIS1 (91% identical), rabbit FIS1 (86% identical), rat Fis1 (80% identical), tropical clawed frog fis1 (75% identical), zebrafish fis1 (68% identical), Drosophila melanogaster Fis1 (49% identical), Caenorhabditis elegans fis-2 (37% identical), and 1 more.
Diseases named in the same sentence as FIS1 in open-access papers:
FIS1 is named in the same sentence as 126 diseases in open-access papers, as found by Europe PMC text mining. Sharing a sentence is not in itself a finding about the gene and the disease. The quoted sentences say what the papers report.
diabetes (19 papers, 2014 to 2025). "In contrast, knockdown of fission-related molecules (Drp1/Fis1) ameliorate insulin resistance of diabetes-susceptible cybrid cells." (PMID 30363990, 2018). "To examine the causal role of mitochondrial dynamics in insulin resistance relevant to mtDNA variants, we established cybrid cell harboring diabetes mellitus- (DM-) susceptible mtDNA haplogroup B4 (thereafter DM cybrid) and overexpressed Mfn1, Mfn2, Drp1, and Fis1 in cybrid B4." (PMID 30363990, 2018). "To address whether mtDYN plays a causal role in regulating cellular IR and serves as a potential therapeutic target, we have bidirectionally manipulated the expression of dynamic proteins, including MFN1, MFN2, DRP1, and FIS1 in cybrid cell harboring diabetes-susceptible haplogroup B4." (PMID 30363990, 2018). "Here, we found that diabetes downregulated the expression of Fis1 and also significantly upregulated the signal of mitophagy, probably because the decline of Fis1 expression further hindered the normal process of mitophagy." (PMID 36012573, 2022). "Levels of Fis-1 land Mfn-1 were significantly reduced in the Diabetes+Dapa group compared with the diabetes group (P < 0.05)." (PMID 36068525, 2022). "Depletion of either DRP1 or mitochondrial fission 1 protein (FIS1) attenuated high glucose-induced inhibition of eNOS activity, likely by reducing mitochondrial ROS production in diabetes." (PMID 32547400, 2020). "It has been found that insulin secretion in INS1 cells is reliant on Fis1 level and dysregulation of interface between nutrient input and insulin secretion is highly impacted in type 2 diabetes mellitus." (PMID 31053718, 2019). "Furthermore, miR-484 targets the mitochondrial fission gene Fis1, and since mitochondrial fission is increased during diabetes and contributes to circulating insulin levels, downregulation of miR-84 drives the pathogenesis of IR." (PMID 34776961, 2021). "CLOCK–OPA1/Fis1–mitophagy may be a novel and important target for diabetes therapy." (PMID 36012573, 2022). "The mRNA and protein levels of Drp1, Fis1, and MFF were significantly increased in T2DM rat hearts compared to the control group, whereas the diabetes‐enhanced mitochondrial fission proteins were reversed by exercise training." (PMID 37721125, 2023). "Some examples include inhibiting PRMT1/ATF5 in neuroblastomas, increasing the level of ATF5 inhibition-related miRNAs in gliomas, targeting the Fis-1/ATF5 axis in metabolic diseases, or targeting ATF5 in diabetes." (PMID 35806136, 2022). "In contrast, type 2 diabetes mellitus (T2DM) increased the expression of CLOCK and impaired the mitochondrial quality (mitochondrial networks, OPA1, Fis1, and mitophagy), as well as induced apoptosis." (PMID 36012573, 2022). "We stained kidney cortex sections isolated from STZ- and control WT and miR-379KO mice with respective antibodies to detect EDEM3, FIS1, and TXN1 at 6 and 24 weeks after diabetes onset." (PMID 33398021, 2021). "These analyses revealed that diabetes significantly reduced the expression of OPA1 (p < 0.001) and Fis1 (p < 0.01) in the liver, suggesting that diabetes impaired mitochondrial dynamics, which is consistent with the abnormal mitochondrial networks and morphology observed in diabetic mice." (PMID 36012573, 2022). "The expressions of both Fis1 and Txn1 were significantly decreased in WT-STZ mice, but not in miR-379KO-STZ mice, compared to their respective nondiabetic controls at 6 and 24 weeks after diabetes (for Fis1) and at 1 week post diabetes for Txn1." (PMID 33398021, 2021). "Together, these results suggest that adaptive mitophagy is regulated through Fis1 targeted by miR-379 in MMC, and that reduction of adaptive mitophagy due to increased miR-379 in diabetes leads to reduced mitochondrial quality and contributes to mitochondrial dysfunction." (PMID 33398021, 2021).
diabetes (continued). "In cardiomyocytes from a mouse model of diabetes, FUNDC1 was highly expressed and might promote MAM formation by interacting with IP3R2, thereby increasing Ca2+ and FIS1 expression in mitochondria, ultimately leading to mitochondrial dysfunction and impaired myocardial structure and function." (PMID 39506876, 2024). "However, we found that diabetes reduced the expression of OPA1 (p < 0.001) and Fis1 (p < 0.01), indicating that diabetes not only decreases mitochondrial fusion but also decreases mitochondrial fission." (PMID 36012573, 2022).
Hyperglycemia (19 papers, 2011 to 2025). An increased concentration of glucose in the blood. "Through qPCR analysis, we observed an upregulation in genes associated with mitochondrial fission (Drp1, Mff, and Fis1) following hyperglycemia treatment." (PMID 38818468, 2024). "Under hyperglycemia/oxidative stress, Drp1/Fis1-dominant fission drives fragmentation, cytochrome-c release, and barrier leak; pharmacologic or genetic Drp1 restraint reduces permeability and improves endothelial migration/repair." (PMID 41465410, 2025). "In the retinal vasculature, hyperglycemia and oxidative stress excessively activate Drp1/FIS1, shifting the dynamic equilibrium toward excessive fission and mitochondrial fragmentation." (PMID 41465410, 2025). "qPCR analysis revealed that Pgam5 siRNA transfection led to the downregulation of hyperglycemia-induced Drp1, Mff, and Fis1 expression." (PMID 38818468, 2024). "Previous studies reported that silencing FIS1 or Drp1 expression prevents hyperglycemia-induced ROS production and network fragmentation in endothelial cells." (PMID 37561129, 2023). "For example, reducing hyperglycemia-induced aberrant overexpression of Drp1 and Fis1 by combined siRNA approaches can effectively prevent mitochondrial breakage, improve mitochondrial respiration function and inhibit the apoptosis of RECs." (PMID 37670891, 2023). "Paradoxically, one study showed that FIS1 decreased after ischemia/reperfusion, whereas hyperglycemia resulted in a distinct increase of FIS1 expression after 24 h of reperfusion." (PMID 35571256, 2022). "In the present study, the changes in MFN1 and FIS1 in our HFD+STZ animals are consistent with previous studies on hyperglycemia-induced mitochondrial fission and fragmentation." (PMID 36297069, 2022). "It is also true for VLD effect in high glucose‐treated HUVECs, that is, VLD significantly inhibited high glucose‐induced up‐regulation of Drp1 and Fis1 under hyperglycaemia conditions." (PMID 30444033, 2019). "Recently, we also reported that hyperglycemia in CPCs alters mitochondrial dynamics and increases the expression of fission-related proteins, including mitochondrial fission 1 protein (Fis1) and Drp1." (PMID 30002788, 2018). "Pretreatment of hCPCs with MHY-1684 dramatically reduced hyperglycemia-related mitochondria fission via attenuating the activation of Drp-1 and Fis-1." (PMID 30002788, 2018). "Macrophage content and the smooth muscle cell content in atherosclerotic lesions were higher in mice transduced with Fis1 shRNA starting from 6 weeks of hyperglycemia exposure and further aggravated following 20 weeks of hyperglycemia exposure, compared to the control shRNA group." (PMID 40135829, 2025). "Both in vivo and in vitro experiments suggest that Fis1 may play a critical role in hyperglycemia‐induced vascular endothelial injury." (PMID 40135829, 2025). "Furthermore, Drp1 and its GTPase activity are increased in hyperglycemia, and here, we show that Fis1 interaction with Drp1 and mitochondrial localization of Drp1 are also elevated." (PMID 35399705, 2022). "On the contrary, inhibition expression of mitochondrial fission protein 1 (FIS1) or DRP1 could alleviate the hyperglycemia-induced reduction in eNOS activity and NO bioavailability." (PMID 36613786, 2022). "Similarly, Drp1 receptor protein Fis1 also remained elevated even when the hyperglycemia was replaced by normal glycemia." (PMID 35399705, 2022). "Moreover, VLD reduced the expression of Drp1 and Fis1, blocked Drp1 translocation into mitochondria, and blunted mitochondrial fragmentation induced by hyperglycaemia." (PMID 30444033, 2019). "Importantly, MHY-1684 attenuated mitochondrial ROS generation during hyperglycemia and significantly reduced mitochondrial fragmentation via regulating Drp-1 and Fis-1." (PMID 30002788, 2018).
Hyperglycemia (continued). "It has been reported that the anti-diabetic drug dipeptidyl peptidase 4 inhibitor vildagliptin reduced the expression of DRP1 and Fis1, blocked the movement of DRP1 to the mitochondria, and slowed mitochondrial fragmentation induced by hyperglycemia." (PMID 37760030, 2023). "In both diabetic db/db mice and hyperglycaemia‐exposed HUVECs, we confirmed that VLD reduces Drp1 and Fis1 expression and subsequently mitochondrial fission mediated via an AMPK‐dependent manner." (PMID 30444033, 2019). "As we observed a reduction in Fis1 in HFD male offspring, it is possible that this could be one of the mechanisms by which hyperglycemia is observed in developmentally programmed offspring." (PMID 39000422, 2024). "Reversal of hyperglycemia by normal glycemia does not ameliorate GTPase activity of Drp1 and its interaction with Fis1, and increased Drp1 accumulation in the mitochondria continues to fragment them." (PMID 35399705, 2022). "In contrast to DRP1, there was no significant change in the expression of FIS1 in pMCAO or hyperglycemia model." (PMID 35571256, 2022).
Sepsis (16 papers, 2020 to 2025). Sepsis is defined as life-threatening organ dysfunction caused by a dysregulated host response to infection. "In other words, elevations of parkin, Mfn2, and PGC-1α appear to protect against organ dysfunction in animal models of sepsis, whereas Fis1 is associated with sepsis severity and multiple organ dysfunction." (PMID 34055831, 2021). "We found that the serum Fis1/parkin ratio is an independent risk factor and a predictor of 28-day mortality in patients with sepsis." (PMID 34055831, 2021). "Additionally, Fis1/parkin ratio was proved to be an independent risk predictor for patients with sepsis." (PMID 34055831, 2021). "While levels of mitochondrial fusion-related genes Opa1 and Mfn2 were not different between groups, levels of mitochondrial fission-related genes, Fis1 and Dnm1l, were increased in Sepsis by 16% (p = 0.0197) and 42.1% (p = 0.0416), respectively." (PMID 41315622, 2025). "Opa1 expression, contributing to mitochondrial fusion processes, was upregulated with sepsis (P < 0.01 vs. healthy control mice), whereas the expression of Fis1 remained unaltered (P = 0.2)." (PMID 41385533, 2025). "In this study, we found that FIS1 was downregulated in the peripheral blood transcriptome results of sepsis, with statistically significant differences." (PMID 38755528, 2024). "Using the GEO database and downloading GSE65682 for 28-day survival analysis, we found that sepsis patients with low expression of FIS1 had a higher 28-day survival rate compared to the high expression group (P < 0.05)." (PMID 38755528, 2024). "The area under the receiver operating characteristic (ROC) curve of the Fis1/parkin ratio was greater than that of Fis1, parkin, Mfn2, and PGC-1α levels as well as that of the Fis1/Mfn2 and Fis1/PGC-1α ratios for prediction of 28-day mortality due to sepsis." (PMID 34055831, 2021). "This study aimed to assess the prognostic value of the Fis1/parkin ratio as a biomarker in patients with sepsis." (PMID 34055831, 2021). "Fis1/parkin ratio was found to be an independent predictor of 28-day mortality in patients with sepsis." (PMID 34055831, 2021). "We found an increase in pro-fission-related genes Drp1 and Fis1, which could promote aberrant mitochondrial fission and may contribute to the impaired long-term efficiency of mitochondrial respiration after sepsis." (PMID 41315622, 2025). "Based on this, we hypothesize that the low expression level of FIS1 may become a new focus in sepsis research, and it shows high sensitivity and specificity for sepsis." (PMID 38755528, 2024). "Thus, the sepsis-like energy deficit mainly stimulated higher Fis1 expression, contrary to sepsis." (PMID 37106730, 2023). "An elevation of Fis1/parkin ratio could be used to alert clinicians that mitochondrial dysfunction is existed, and clinical adjustments are needed to prevent the progression of sepsis." (PMID 34055831, 2021). "In sepsis-induced AKI, the inhibition of Drp1-Fis1 pathway by reducing lactate levels and Fis1 lactylation attenuate the damage." (PMID 39267971, 2024). "We compared the gene expression levels of both groups and found that FIS1, FKBP8, GLRX5, and GUK1 were underexpressed in the sepsis group but overexpressed in the SIRS group." (PMID 38755528, 2024). "Mitochondria-related genes (FIS1, FKBP8, GLRX5, GUK1) were underexpressed in the sepsis group, negatively correlated with survival, and mainly distributed in immune cells." (PMID 38755528, 2024). "Conversely, reducing lactate levels and fission 1 protein (Fis1) lactylation mitigates SAKI, revealing a novel mechanism linking lactate and organ damage in sepsis." (PMID 39234245, 2024). "In this study, we identified for the first time that four mitochondrial genes (FIS1, FKBP8, GUK1, GLRX5) can significantly impact the prognosis of sepsis patients, with high sensitivity and specificity for sepsis." (PMID 38755528, 2024).
Sepsis (continued). "Nevertheless, Fis1 mRNA increased by ~4-fold in the SPF group compared with the SF group (p < 0.05), and was lower in the Sepsis group than the SPF group (p < 0.05)." (PMID 37106730, 2023). "Our results showed that the expression of Drp1 and Fis1 was increased, while OPA1, Mfn1 and Mfn2 were decreased in the intestinal epithelium during sepsis, indicating increased mitochondrial fission and insufficient mitochondrial fusion." (PMID 36581806, 2022). "In our study, patients with sepsis presented with significantly decreased serum levels of parkin, Mfn2, and PGC-1α and significantly increased serum Fis1 level and Fis1/parkin, Fis1/Mfn2, Fis1/PGC-1α ratios." (PMID 34055831, 2021). "Using an established LPS model of sepsis in 5 to 7-week-old female BALB/c mice, we evaluated the role of Drp1/Fis1 interaction in sepsis-mediated encephalopathy." (PMID 31987040, 2020). "This project evaluates the role of Drp1/Fis1 interaction in mediating mitochondrial failure and subsequent BBB dysfunction in the setting of sepsis." (PMID 31987040, 2020). "While research on histone lactylation is more prevalent, beyond the investigation of nonhistone Fis1 lactylation, macrophage-derived nonhistone HMGB1 lactylation in sepsis has also been reported." (PMID 39234245, 2024).